TLR2 (toll like receptor 2)
Diseases named in the same sentence as TLR2 in open-access papers (continued):
Sharing a sentence is not in itself a finding about the gene and the disease.
colorectal cancer (continued). "To understand the mechanism, we examined the expression levels of Fas, c-Jun and TLR2 in the four types of colorectal carcinoma cells by qRT-PCR." (PMID 29079852, 2017). "Single nucleotide polymorphisms (SNPs) in TLR2 and TLR4 have been associated with childhood asthma, chronic obstructive pulmonary disease (COPD) and colorectal cancer." (PMID 27307950, 2016). "Expression of the artificial TLR2 transcript (TLR2) apparently promoted the invasion and migration of colorectal carcinoma cells." (PMID 23866094, 2013). "For example, Bacteroides produce Polysaccharide A against colorectal cancer via TLR2 signaling." (PMID 38847243, 2025). "Thus, a single IHC stain for TLR2/4/5 on a colorectal carcinoma section largely recapitulates the manual counts of cytotoxic and helper T cells in both tumor nests and stroma." (PMID 41465346, 2025). "In colorectal cancer, TLR2 expression may contribute to sporadic carcinogenesis and TLR4 may increase cancer cell survival." (PMID 38709790, 2024). "Additionally, inhibition of TLR2 signalling was demonstrated to suppress colorectal cancer cell growth, revealing a potential key role of TLR2 in colorectal tumorigenesis." (PMID 35484352, 2022). "Of note, TLR2 is also implied in the development of chemoresistance in colorectal cancer." (PMID 33321934, 2020). "As a consequence, TLR2 knockout or knockdown inhibits the proliferation of colorectal cancer cells, leading to cell cycle arrest in the G1 phase and thereby significantly impairing the development of both inflammation-related and sporadic colorectal cancer in preclinical models." (PMID 33321934, 2020). "A recent study confirming downregulation of TLR4 and upregulation of TLR2 in colorectal carcinomas may partly explain these conflicts by indicating contrast effects of different TLRs on tumor pathogenesis." (PMID 31675995, 2019). "The results of the present study indicated that there is a specific association between HCMV and the occurrence and development of colorectal cancer, which may be facilitated by the TLR2 signaling pathway." (PMID 25435993, 2015). "Furthermore, the expression of IE1–72 in colorectal cancer tissues was found to correlate with TLR2 and TLR4, and the correlation coefficients were 0.515 and 0.462, respectively." (PMID 25435993, 2015). "The CD68 antigen, expressed by immature dendritic cells and macrophages that are ready to take up antigen, is included in our list of genes up-regulated in MSI-H colorectal cancer, as is the TLR-2 gene, one of a family of receptors to which HSP's bind to activate dendritic cells." (PMID 15298707, 2004). "In addition, recent pre-clinical work using CAR-T cells containing an anti-CD318 single-chain variable fragment (anti-CD318 scFv), CD3ζ, CD28, and Toll-like receptor 2 (TLR2) domains, shows great promise as a novel strategy for the treatment of colorectal cancer." (PMID 39840036, 2024). "The role PGN in enhancing the radiation-induced antitumorigenic effect and in reducing the side effects of radiotherapy to the intestine is clinically relevant, and could potentially alter the current standard-of-care of colorectal cancer patients to include TLR2 agonists." (PMID 27708223, 2016). "Toll-like receptors (TLRs), particularly TLR1, TLR2, and TLR4, play a multifaceted role in the progression of colorectal cancer (CRC)." (PMID 41419456, 2025). "Actinomyces has been shown to the production of various immunological and microbial-related genes, such as TLR2, TLR4, and NF-B, which support the growth of colorectal cancer by controlling inflammation by activating the downstream TLR4/NF-B pathway." (PMID 38445094, 2024). "Another study discovered that in patients with colorectal cancer liver metastases, the expression of CXCR4 CXCR7, TLR2/TLR4, and PD-1/PD-L1 was significantly increased in metastatic liver tissues compared to unaffected liver tissues." (PMID 34568309, 2021).
colorectal cancer (continued). "By querying GENT2 datasets, we identified the gene expression level of TLR2 and TLR4 as being substantially increased in colorectal cancer." (PMID 32050430, 2020). "Among all the TLRs, expression of TLR2 and TLR4 mRNA is increased significantly in colorectal cancer based on the bioinformatics analysis in the GENT2 database." (PMID 32050430, 2020). "Expression of TLR2 or TLR4 mRNA is higher in patients’ tumor samples, which was suggested to be a marker in human colorectal cancer." (PMID 32050430, 2020). "The molecular mechanism for protection against colorectal cancer (CRC) provided by B. fragilis is dependent on polysaccharide A (PSA) production and is mediated by TLR2 signaling." (PMID 32685120, 2020). "Colorectal cancer tissues usually have higher TLR2 gene expression levels than normal colorectal mucosa from the same patient, and activation of TLR2 and TLR4 in previous studies of colorectal cancer has also been shown to promote tumor cell proliferation." (PMID 32256204, 2020). "This study aimed to explore the prognostic value of TLR2 and TLR4 tumor expressions in colorectal cancer patients." (PMID 32424768, 2020). "In 25 positive cases of IE1–72, there were 24 positive cases of TLR2 and 24 positive cases of TLR4 in the colorectal cancer samples." (PMID 25435993, 2015). "The expression levels of TLR2, TLR4, NF-κB and TNF-α in colorectal cancer and adenoma were also higher than those in the control tissues." (PMID 25435993, 2015). "Immunohistochemical analysis revealed that the expression of IE1–72, TLR2, TLR4, NF-κB and TNF-α protein in colorectal carcinoma was significantly higher than that in the normal tissues." (PMID 25435993, 2015). "Colorectal cancer tissues have higher TLR1, TLR2, TLR4 and TLR8 gene expression levels in general than do the normal colon mucosa from the same patient (p < 0.05)." (PMID 25547486, 2014). "Furthermore, these three genes-TLR2, IFNG, and CD163-are abundantly expressed in colorectal cancer (CRC) tumor tissues." (PMID 41300749, 2025). "Our work indicates that if TLR2 activation by EVs do not disrupt healthy intestinal epithelium, TLR2 activation can have a deleterious impact in the context of colorectal cancer." (PMID 33408714, 2020). "In an in vitro sporadic colorectal cancer cell experiment, TLR2 protein in the TLR2 knockdown group was significantly downregulated, and TLR2 knockdown significantly inhibited the proliferation of HCT116 and HT29 colorectal cancer cells, resulting in G1 phase arrest." (PMID 32256204, 2020). "Instead of TLR2 or TLR4, BGN (which is significantly increased in colon cancer) may be a more useful marker in human colorectal cancer." (PMID 32050430, 2020). "HCMV infection was found to correlate with the expression of TLR2 and TLR4 in colorectal cancer." (PMID 25435993, 2015). "Further, F. nucleatum may impact colorectal cancer through TLR4 and TLR2." (PMID 32318067, 2020). "Therefore, this study aimed to clarify the prognostic roles of TLR2 and TLR4 in colorectal cancer." (PMID 32424768, 2020). "Furthermore, it has been observed that Anaerobic Peptostreptococcus activates Toll-like receptors 2 and 4 (TLR2 and TLR4), resulting in elevated intracellular reactive oxygen species (ROS) levels, which subsequently facilitate cell proliferation during the progression of colorectal cancer (CRC)." (PMID 39959156, 2025). "However, TLR2 knockdown did not affect the growth of colorectal carcinoma cells." (PMID 23866094, 2013). "However, the role of TLR2 in the development of colorectal cancer has not been studied." (PMID 20885960, 2010).
gastric cancer (55 papers, 2012 to 2026). A primary or metastatic malignant neoplasm involving the stomach. "The receiver operating characteristic (ROC) curve analysis was designed to determine the diagnostic accuracy of TLR2 expression in gastric cancer patients compared to controls." (PMID 36982898, 2023). "Research by Huan Yang’s team has shown that TLR2 plays a key role in promoting the invasion of SGC-7901 human gastric cancer cells and is also associated with metastasis." (PMID 36982898, 2023). "Several studies pointed out that TLR2 polymorphisms are associated with an increased risk for gastric cancer, but this association also depends on ethnicity and geographic area." (PMID 35204842, 2022). "An association of TLR2-196 to -174 del polymorphism with susceptibility to gastric cancer was demonstrated in Brazilian population (de Oliveira and Silva, 2012)." (PMID 34484153, 2021). "TLR2 is involved in the pathogenesis of gastric cancer, and high levels of TLR4 are also associated with a higher risk of this tumor type." (PMID 34686626, 2021). "Recent study indicated that up-regulated TLR2 was associated with advanced stage, distant metastasis, and poor clinical outcomes in gastric cancer." (PMID 33015704, 2020). "Mutation present in both alleles of the TLR2 2029C/T and 2258G/A SNPs were associated with susceptibility to gastric carcinoma in China42." (PMID 32753695, 2020). "As in the case of gastric biopsy samples, the risk of gastric cancer due to peptic ulcers differs among individuals who harbor different TLR2 gene polymorphisms, depending also on ethnic features." (PMID 30863783, 2019). "In another study amongst 47 gastric cancer samples studied using immunohistochemistry, a high TLR2 expression associated with metastatic disease." (PMID 31467388, 2019). "Different ethnic studies performed on gastric biopsy samples identified that genetic polymorphism in TLR2 is associated with an increased risk of gastric cancer, with variations between different geographic areas and populations." (PMID 30863783, 2019). "Increased STAT3 pathway activation and TLR2 expression were also associated with poor survival in gastric cancer patients." (PMID 26064948, 2015). "PCR primer sequences and thermal conditions used for genotyping of CD14 and TLR2 polymorphisms in gastric cancer patients and functional dyspepsia controls." (PMID 23565226, 2013). "In a Japanese population, subjects with the −196 to −174del/del genotype of TLR2 were shown to be about six times as susceptible to gastric cancer compared to those with the corresponding WT alleles." (PMID 22442665, 2012). "However, in another study, the expression of TLR1, TLR2, TLR4, TLR5 and TLR6 was associated with survival in gastric cancer, and only high cytoplasmic TLR2 expression was shown to be significantly associated with a poorer 5-year survival." (PMID 40362298, 2025). "In previous studies, TLR2 was found to be expressed at a high level in most patients with gastric cancer, and high expression of TLR2 was associated with proliferative genes and indicated a poor prognosis, while other studies have also suggested that TLR2 promotes the development of gastric cancer." (PMID 32256204, 2020). "Moreover, TLR2 expression in gastric cancer has been linked to metastatic disease and increased invasion." (PMID 31467388, 2019). "TLR-2 polymorphisms are also involved in areduced response after challenge with mycobacteria, whereasTLR4 polymorphisms are known to be associated with a reduced response to lipopolysaccharide and the development of gastric cancer." (PMID 26771524, 2016). "In contrast, lncRNA H19 acts as a “sponge” for miR-29b, alleviating its inhibitory effect on TLR2 mRNA, upregulating TLR2 expression, and promoting gastric cancer metastasis, suggesting a tumor-promoting function." (PMID 41488647, 2025).
gastric cancer (continued). "In vitro experiments have demonstrated that NETs can activate COX-2 through toll-like receptor 2 (TLR2), thereby enhancing the metastatic potential of gastric cancer cells." (PMID 40387965, 2025). "Of note, Pam3CSK4 was shown to have oncogenic effect in gastric carcinoma cells and TLR2 targeting inhibited gastric tumorigenesis." (PMID 39874349, 2025). "In light of our observations and data in the literature, this study aimed to determine the role of selected TLR-2, -3, -4, and -9 in the immunopathogenesis of patients with newly diagnosed and untreated gastric cancer." (PMID 39273213, 2024). "Aim of the study: This study aimed to determine the role of selected TLR-2, -3, -4, and -9 in the immunopathogenesis of patients with newly diagnosed and untreated gastric cancer." (PMID 39273213, 2024). "Our research results indicate that TLR-2, -3, -4, and -9 play an important role in the immunopathogenesis of gastric cancer." (PMID 39273213, 2024). "In our work, we focused on examining differences in the expression of TLR-2, -3, -4, and -9 in two subtypes of gastric cancer, intestinal and diffuse, to better understand their potential impact on the course of the disease." (PMID 39273213, 2024). "Based on the obtained results, we have shown that patients with gastric cancer are characterized by a higher percentage of all tested populations of peripheral blood immune cells expressing TLR2 in relation to patients from the control group." (PMID 36982898, 2023). "Based on the obtained results, we showed that patients with gastric cancer are characterized by a higher percentage of TLR2 occurrence on all tested immune cell populations compared to patients from the control group." (PMID 36982898, 2023). "On the other hand, in the studies conducted by the Xu team, in which the researchers assessed the level of TLR expression in CD8+ lymphocyte cells, the results obtained during the study indicated the regulation of downstream TLR2 in gastric cancer patients." (PMID 36982898, 2023). "To further prove the function of NETs in regulating COX-2 through TLR2 in gastric cancer, we used PGE2 to perform rescue experiments." (PMID 37153547, 2023). "The aim of this study was to determine the prevalence of TLR2 on T lymphocytes, B lymphocytes, monocytes, and dendritic cells in patients diagnosed with gastric cancer, with particular emphasis on the stage of the disease." (PMID 36982898, 2023). "The studies presented in this article indicate a significant role of TLR2 in the development and progression of gastric cancer." (PMID 36982898, 2023). "The analysis of the concentration of the soluble form of TLR2 (sTLR2) using the ELISA immunoassay showed a four-fold increase in its concentration in the serum of patients with gastric cancer compared to healthy patients." (PMID 36982898, 2023). "Based on the obtained results, we have shown that the percentage of all tested populations of peripheral blood immune cells expressing TLR2 is statistically significantly higher in patients with gastric cancer compared to the control group." (PMID 36982898, 2023). "PGE2 was added to gastric cancer cells after TLR2 inhibition to simulate COX-2 up-regulation, called experimental group 2." (PMID 37153547, 2023). "Observations related to elevated TLR2 levels were also carried out by the West team, which in its research tried to determine the clinical utility of TLR2 assessment in gastric cancer." (PMID 36982898, 2023). "Recent studies confirm the important role of TLR2 in promoting carcinogenesis, including the development and progression of gastric cancer." (PMID 36982898, 2023). "In the next stage of the study, we analyzed the percentage of T and B lymphocytes, dendritic cells, and peripheral blood monocytes expressing TLR2 in patients diagnosed with gastric cancer compared to patients in the control group." (PMID 36982898, 2023).
gastric cancer (continued). "The Transwell assay indicated that the metastatic potential of gastric cancer cells was initially suppressed and then promoted, highlighting that TLR2 is essential to the mechanism by which NETs regulates COX-2." (PMID 37153547, 2023). "18β-GA can inhibit the metastasis of human gastric cancer in vitro, which is regulated by the TLR2 signaling pathway." (PMID 36313350, 2022). "Some studies assessing the role of polymorphisms in TLR2, TLR4, TLR5, NOD1 and NOD2 in gastric cancer have been published." (PMID 33879265, 2021). "The aim of our study was to assess the association of common polymorphisms in TLR2, TLR4, TLR5, NOD1 and NOD2 with gastric cancer in H. pylori infected subjects." (PMID 33879265, 2021). "The aim of this study was to assess if polymorphisms of TLR2, TLR4, TLR5, NOD1 and NOD2 genes are associated with gastric cancer, in particular in individuals infected with H. pylori." (PMID 33879265, 2021). "The genotypes TLR2 ins/del and del/del were found more often in the individuals with gastric cancer than the healthy individuals." (PMID 34484153, 2021). "Another study in gastric cancer provided additional evidence supporting the role of TLR2 in the inflammatory microenvironment and in promoting tumor progression." (PMID 32426275, 2020). "TLR2 promotes gastric cancer progression by stimulating proliferation and inhibiting the apoptosis of cancer cells through the activation of the NF-κB, PI3K/AKT, ERK1/2, and JNK MAPK pathways, without inducing an inflammatory response." (PMID 33321934, 2020). "There is strong evidence suggesting the role of TLR2 in the development of gastric cancer despite ethnic differences." (PMID 30863783, 2019). "In gastric cancer, TLR2 and TLR9 are thought to account for the invasive abilities of H. pylori-mediated infection, and in papillary thyroid cancer, TLR3 overactivation is linked to cancer progression." (PMID 31314777, 2019). "Invasion and angiogenesis of gastric cancer cells was described to be mediated by cyclooxygenase-2 (COX-2) after TLR2 and TLR9 activation, leading to inflammation and cancer progression." (PMID 26134824, 2015). "In the setting of H. pylori infection, gene expression of TLR2 and TLR4 is elevated in H. pylori-positive gastric patients, and TLR2 and TLR4 gene polymorphisms are associated with an increased risk of gastric cancer." (PMID 26064948, 2015). "While most reports describe the anti-tumor functions of TLR2, opposing results have been reported in a context-dependent manner with TLR2 playing an important tumor-promoting role in gastric cancer." (PMID 25309546, 2014). "Effect of Helicobacter pylori infection and TLR2, TLR4 and CD14 polymorphisms on gastric cancer risk." (PMID 23565226, 2013). "Individual studies included in the meta-analysis of TLR2, TLR4 and CD14 polymorphisms and gastric cancer." (PMID 23565226, 2013). "Association between TLR2, TLR4 and CD14 polymorphisms and risk of gastric cancer in ethnic Chinese individuals." (PMID 23565226, 2013). "In conclusion, this meta-analysis provided statistical evidence that the TLR2 and TLR4 polymorphisms were associated with cancer risk, particularly for gastric cancer." (PMID 24376595, 2013). "Recently, the circulating levels of soluble forms of TLR2, TLR4, and TLR9 were positively associated with advanced stages of gastric cancer, including an upregulation of the protein levels on circulating immune cells in patients with gastric cancer compared to those with premalignant lesions." (PMID 40362298, 2025). "Among these, the selection of 19 HERSRDEGs such as ANGPT2, ERG1, CD36, NOX4 and TLR2, provides critical insights into the potential roles these genes may play in gastric cancer pathophysiology." (PMID 40061897, 2025). "Similar to previous studies, our study also showed that TLR2 is involved in tumor progression in gastric cancer, but we demonstrated that NETs could also act as a ligand of TLR2 to initiate downstream inflammatory factors." (PMID 37153547, 2023).